MMP14 (matrix metallopeptidase 14)
Diseases named in the same sentence as MMP14 in open-access papers (continued):
Sharing a sentence is not in itself a finding about the gene and the disease.
gastric cancer (continued). "MMP-14 plays a crucial role in cell invasion; hence, when YY1-induced MMP-14 expression is suppressed by miR-584-3p through methylation of the YY1 binding site in the MMP-14 promoter, the tumorigenesis and aggressiveness of gastric cancer cells were suppressed." (PMID 37444616, 2023). "It was also reported that MMP2 in renal carcinoma cells, MMP9 and MMP14 in osteosarcoma cells could increase soluble MICA and MMP9 specific inhibitor could increase MICA/B and ULBP2 in some kinds of gastric cancer cells." (PMID 34253166, 2021). "In gastric cancer, myeloid zinc finger 1 (MZF1) upregulates MMP14 expression, which can be competitively inhibited by miR-337-3p because this miRNA can bind to the same binding site of MZF1 on the promoter of MMP14." (PMID 34297054, 2021). "In gastric cancer cells, MZF1 upregulates MMP14 expression by directly binding to its promoter." (PMID 31963147, 2020). "MiRNA-337-3p inhibits gastric cancer progression by downregulating MZF1 activity via a specific mechanism, where miRNA-337-3p binds to the promoter region of MMP14 adjacent to its MZF1 binding site and represses the MZF1-induced expression of MMP14." (PMID 31963147, 2020). "Therefore, this study aimed to investigate the relationship between MMP14 and PROX1 in gastric cancer and to explore their values as prognostic biomarkers." (PMID 31560170, 2019). "Variable levels of MMP14 expression in MKN‐7, MKN‐28, and TMK‐1 accompanied by a nearly absent PROX1 expression may indicate a functional connection between MMP14 and PROX1 in gastric cancer as well, although in AGS both MMP14 and PROX1 were expressed." (PMID 31560170, 2019). "Due to the significant membrane-binding properties of MMP-14, its serum levels do not necessarily directly reflect its overall expression in malignant disease, including in gastric cancer." (PMID 30532247, 2018). "Moreover, treatment with GSK343 and A-366 prevented the gastric cancer cells from increased enrichment of H3K27me3 and H3K9me2 and decreased binding of YY1 to MMP-14 promoter induced by miR-584-3p over-expression." (PMID 28827574, 2017). "To address the hypothesis that YY1 might influence the MMP-14 expression, we performed the YY1 over-expression and knockdown experiments in gastric cancer cells." (PMID 28827574, 2017). "Meanwhile, miR-337-3p is under-expressed in human gastric cancer, and suppresses the transcription of MMP-14 via epigenetically suppressing the binding of MZF1 to its promoter, resulting in decreased growth, invasion, metastasis, and angiogenesis of gastric cancer cells in vitro and in vivo." (PMID 27259238, 2016). "This study extends our knowledge about the regulation of MMP-14 at transcriptional level, and suggests that MZF1 and miR-337-3p may be of potential values as novel therapeutic targets for human gastric cancer." (PMID 27259238, 2016). "To figure out the possible mechanisms of how IGFBP3 regulate the invasiveness of gastric cancer cells, we examined the mRNA levels of MMP2/MMP7/MMP9/MMP14, TIMP1/TIMP2, uPA and its receptor uPAR, all of which are invasion-related factors, especially in gastric cancer." (PMID 24386080, 2013). "Since MMP-14-mediated degradation of ECM occurs throughout the angiogenic process and contributes to vascular regression, we further demonstrated that sub-cytotoxic MJ attenuated the angiogenic capabilities of gastric cancer cells." (PMID 23394613, 2013). "By contrast, miR-584-3p inhibits gastric cancer (GC) progression by suppressing Yin Yang 1 (YY1), which binds to MMP14 promoter to improve its expression." (PMID 35348905, 2022). "Additionally, in the immunofluorescence analysis, the MMP14 expression in MKN‐7 and MKN‐28 accompanied by a nearly absent PROX1 expression may indicate a functional connection between MMP14 and PROX1 in gastric cancer as well." (PMID 31560170, 2019). "Only a few studies of MMP-14 in gastric cancer exist and none examined serum levels." (PMID 30532247, 2018).
gastric cancer (continued). "Furthermore, miR-584-3p is under-expressed in human gastric cancer, and suppresses the transcription of MMP-14 via epigenetically suppressing the binding of YY1 to its promoter, resulting in decreased growth, invasion, metastasis, and angiogenesis of gastric cancer cells in vitro and in vivo." (PMID 28827574, 2017). "Finally, endogenous MMP-14 expression, both transcript and protein, was increased or decreased by over-expression and knockdown of MZF1 in gastric cancer cells, suggesting that MZF1 may facilitate the MMP-14 expression by activating transcription." (PMID 27259238, 2016). "Furthermore, MMP14 expression appears to be higher in gastric cancer tissues compared to noncancerous mucosa, indicating a worse prognosis in cancer patients with a high MMP14 expression compared to patients with a low MMP14 expression." (PMID 31560170, 2019). "Western blot indicated that administration of sub-cytotoxic (0.1 and 0.2 mM) MJ resulted in a decrease in the expression of MMP-14, but not of MMP-7 or MMP-9, in cultured gastric cancer SGC-7901 and MKN-45 cells." (PMID 23394613, 2013). "Real-time quantitative RT-PCR revealed the decreased transcript levels of MMP-14, but not of MMP-7 or MMP-9, in gastric cancer cells treated with sub-cytotoxic MJ." (PMID 23394613, 2013). "Western blot and real-time quantitative RT-PCR indicated that the expression of Sp1, MMP-14, and VEGF was significantly higher in gastric cancer tissues than that of adjacent non-neoplastic tissues." (PMID 23394613, 2013). "In this study, we found that sub-cytotoxic MJ selectively down-regulated the expression of MMP-14, but not of MMP-7 and MMP-9, in gastric cancer cells." (PMID 23394613, 2013). "Importantly, YY1 directly bond to MMP-14 promoter to increase its expression, resulting in elevated levels of VEGF and active MMP-2, but not of Snail, in gastric cancer cells." (PMID 28827574, 2017). "In addition, treatment of gastric cancer cells with RNase H, but not with RNase A, abolished the enrichment of AGO2 on the MMP-14 promoter in." (PMID 28827574, 2017).
pancreatic cancer (56 papers, 2008 to 2025). "In GSE21510 and GSE28735 datasets, the higher expression level of MMP14 was associated with worse prognosis in patients with pancreatic cancer." (PMID 32950968, 2020). "In another study, MMP14 (MT1-MMP) expression levels were found to be high together with C4.4A and α6β4 integrin in hiTDExs collected from pancreatic cancer cells under hypoxic conditions." (PMID 39928285, 2025). "Previous studies have shown that MMP14 plays a key role in the progression of a variety of malignant tumors, including pancreatic cancer, colorectal cancer and intrahepatic cholangiocarcinoma." (PMID 38898429, 2024). "Treating pancreatic cancer cells PANC1 with macrophage M2‐conditioned medium lead to up‐regulated MMP14 and INHBA expression, suggesting macrophages M2 up‐regulate these genes and can be used as risk predictors." (PMID 35150061, 2022). "For example, some preliminary experiments are needed to expose the mechanism of INHBA and MMP14 expression in pancreatic cancer and their correlation with macrophages M2." (PMID 35150061, 2022). "In summary, our data demonstrate that the exosome-transferred MMP14 is a key mediator for the transmission of gemcitabine resistance in pancreatic cancer." (PMID 35223528, 2022). "In another study, MMP-14 was found to play a mediation role in gemcitabine resistance in in pancreatic cancer cells." (PMID 35586209, 2022). "We discovered that MMP14 expression is higher in pancreatic cancer samples compared with corresponding normal samples, and the38 MMP14 expression is correlated with macrophage M2." (PMID 35150061, 2022). "Because HMGA2 was shown to protect pancreatic cancer cells from DNA damage-induced apoptosis, elevating MMP-14 expression will consequently reduce the effects of gemcitabine by increasing the expression of MMP-14." (PMID 35586209, 2022). "We also revealed the new role of CRABP-II in the regulation of IL8/MMP2/MMP14 pathway to promote pancreatic cancer migration and invasion." (PMID 35260193, 2022). "For example, CD44 regulates MMP14 expression through Snail, leading to pancreatic cancer cell invasion." (PMID 35223528, 2022). "TCGA dataset showed that expression of MMP14 mRNA in pancreatic cancer patients is positively correlated with that of both ARL4C and IQGAP1 mRNA." (PMID 34590580, 2021). "Corresponding to the higher un-responsiveness of pancreatic cancer patients with KRAS mutation or CDKN2A deletion, we found that MMP14 and PKM2 were highly expressed in drug un-responsive patients." (PMID 32950968, 2020). "In the immunohistochemical features, we found that in the 18 pancreatic cancer tissues with highly stained sections of MMP14, 83% pancreatic cancer tissues were also with highly stained sections of PKM2." (PMID 32950968, 2020). "We identified 18 pancreatic cancer tissues were with high MMP14 expression and 40 pancreatic cancer tissues were with low MMP14 expression." (PMID 32950968, 2020). "Based on the average expression levels of MMP14 and PKM2, pancreatic cancer patients were divided into MMP14 and PKM2 high expression group or MMP14 and PKM2 low expression group." (PMID 32950968, 2020). "Transcriptional factor Snail1 is a CD44 downstream target that regulates MMP14 expression and in turn MMP14 is required for pancreatic cancer invasion." (PMID 29747682, 2018). "Knockdown immune‐related genes MMP14 or INHBA decreased the invasion of pancreatic cancer cells, which could also be promoted by MCM." (PMID 35150061, 2022). "Additionally, exosome-transferred MMP14 is a crucial facilitator of gemcitabine resistance in pancreatic cancer." (PMID 36339551, 2022). "In conclusion, this study clarified that invasion of pancreatic cancer cells is promoted by ARL4C, of which expression is induced by KRAS and Wnt signaling, and that association of ARL4C with IQGAP1 and MMP14 at the tips of invasive pseudopods are essential for the invasive ability." (PMID 34590580, 2021).
pancreatic cancer (continued). "The three genes, COL12A1 APOL1 and MMP14, may be vital in mediating the progression of pancreatic cancer." (PMID 33027767, 2020). "However, the associations of MMP14, PKM2 and overall survival of pancreatic cancer patients were unclear." (PMID 32950968, 2020). "Furthermore, we showed that pancreatic cancer patients with both high MMP14 and PKM2 stained sections were with lowest overall survival." (PMID 32950968, 2020). "We thought that the combination of MMP14 with PKM2 could be used as better prognostic markers in patients with pancreatic cancer." (PMID 32950968, 2020). "MMP14 combined with PKM2 could be used as prognostic marker in patients with pancreatic cancer." (PMID 32950968, 2020). "Also, MMP14 and PKM2 were both associated with unfavorable outcomesin pancreatic cancer." (PMID 32950968, 2020). "Also, MMP14 was highly expressed in stage II and grade 3 pancreatic cancer patients." (PMID 32950968, 2020). "Next, the immune‐related prognosis model was established by the expression of immune‐related genes MMP14 and INHBA in pancreatic cancer." (PMID 35150061, 2022). "Effects of MCM and the immune genes MMP14, INHBA on the invasion of pancreatic cancer cells were evaluated by trans‐well assay." (PMID 35150061, 2022). "Then, we applied macrophage conditioned medium to culture pancreatic cancer cell line PANC1, detected the expression of MMP14 and INHBA by qRT‐PCR and Western blot methods." (PMID 35150061, 2022). "An ECM stiffness-induced activation of an MMP-14 and MMP-2/9 cascade has been shown for pancreatic cancer cells and supports our new finding of ECM-triggered MMP activation in BM-covered breast acini." (PMID 33921304, 2021). "Pancreatic cancer tissues were stained with anti-ARL4C, anti-IQGAP1, and anti-MMP14 antibodies in the serial section." (PMID 34590580, 2021). "Invasive pseudopods that we defined in these pancreatic cancer cells highly expressing ARL4C consisted of similar molecules, including cortactin, ARPC2, IQGAP1, and MMP14, which are involved in invadopodia functions." (PMID 34590580, 2021). "We then assessed the expression levels of MMP14 and PKM2 in pancreatic cancer patients with different subtypes." (PMID 32950968, 2020). "The protein expression levels of MMP14 and PKM2 in pancreatic cancer tissues were also varied significantly." (PMID 32950968, 2020). "Further, using commercial tissue microarray, we determined the protein expression levels of MMP14 and PKM2 in Chinese pancreatic cancer patients." (PMID 32950968, 2020). "Interesting, we found six genes E2F7, CDC6, MMP14, PLK1, VASP and PKM2 were significantly correlated with the prognosis of patients with pancreatic cancer in TCGA, GSE71729, GSE78229 and GSE79668 datasets." (PMID 32950968, 2020). "We found that patients with both high MMP14 and PKM2 expression levels were with lowest overall survival in patients with pancreatic cancer." (PMID 32950968, 2020). "Compared with grade 2, the higher expression levels of MMP14 and PKM2 in grade 3 subtype of pancreatic cancer patients were also observed in GSE78829 dataset." (PMID 32950968, 2020). "Those integrated analysis revealed the prognostic significance of MMP14 and PKM2 in patients with pancreatic cancer." (PMID 32950968, 2020). "We found that compared with the adjacent normal tissues, MMP14 and PKM2 were strongly and positively stained in pancreatic cancer tissues." (PMID 32950968, 2020). "Consistent with the bad prognosis of MMP14 and PKM2, pancreatic cancer patients with higher expression of MMP14 or PKM2 had more unfavorable clinical overall survival." (PMID 32950968, 2020). "We found that copper can also up-regulate MMP-2 and MMP-14 expression in human hepatocellular carcinoma cell HUH-7 and human pancreatic cancer cell MIA PaCa-2." (PMID 28881637, 2017). "Knock‐down of MMP14 and INHBA inhibited invasion of pancreatic cancer." (PMID 35150061, 2022).
pancreatic cancer (continued). "Exogenous IL-13 was shown to induce the expression of MMPs including MMP-9, MMP-12, and MMP-14, which were related to pancreatic cancer invasion in IL-13Rα2-positive pancreatic cancer cells independent of STAT6 phosphorylation." (PMID 33804263, 2021). "Expression levels of MMP14 and PKM2 in different subtypes of patients with pancreatic cancer." (PMID 32950968, 2020). "Although, the functions and correlations of MMP14 and PKM2 in pancreatic cancer patients require further elucidation, the combination of MMP14 and PKM2 could be used as better biomarkers to predict the overall survival of pancreatic cancer patients." (PMID 32950968, 2020). "Moreover, the higher expression levels of MMP14 and PKM2 were correlated with the worse prognosis in patients with pancreatic cancer in TCGA, GSE71729, GSE78229 and GSE79668 datasets." (PMID 32950968, 2020). "Furthermore, the prognostic effects of MMP14 and PKM2 are validated in Chinese pancreatic cancer patients." (PMID 32950968, 2020). "Compared with normal tissues, MMP14 and PKM2 wereup-regulated in pancreatic cancer tissues." (PMID 32950968, 2020). "Our results also suggest new prognostic markers of MMP14 and PKM2 in pancreatic cancer." (PMID 32950968, 2020). "Next, we determined the connections of MMP14 and PKM2 in patients with pancreatic cancer." (PMID 32950968, 2020). "Therefore, it can be boldly speculated that MMP14 and these key COL family genes affect metastasis by acting on the ECM-receptor interaction pathway in pancreatic cancer." (PMID 34094925, 2021). "Moreover, MMP14 and PKM2 were highlyexpressed in high grade of pancreatic cancer." (PMID 32950968, 2020).
ovarian carcinoma (53 papers, 2007 to 2025). A malignant neoplasm originating from the surface ovarian epithelium. "MMP14, which plays a key functional role in extracellular matrix breakdown, is known to be mechanistically associated with epithelial ovarian cancer." (PMID 40985572, 2025). "The invading cells were also characterized by the expression of MMP-14, which is considered a master matrix metalloprotease linked to the invasive behaviour of ovarian cancer cells." (PMID 39503511, 2024). "Higher expression of MMP-14 is associated with lower progression and better prognosis of ovarian carcinoma." (PMID 28538838, 2017). "Additionally, a recent study reported that the self-protein matrix metallopeptidase 14 was a major autoantigen in human ovarian cancer, and some Igs likely originated from germline-encoded autoreactive B cells." (PMID 37751306, 2023). "In addition, the membrane bound MMP-14 has been linked to specific roles in ovarian cancer cell-matrix detachment, migration, ECM invasion and angiogenesis." (PMID 35047406, 2021). "Given these open questions, additional studies will be required to elucidate the relationship, if any, between HSP90 and MMP14 in the context of ovarian cancer." (PMID 40985572, 2025). "SH3PXD2A forms a complex with ULK1 and MTOR, and the ULK1-SH3PXD2a-MMP14 axis upregulates the aggressiveness of ovarian cancer." (PMID 38903532, 2024). "VEGFA, PLAU, MMP2, MMP9, and MMP14 expression levels were reduced by stigmasterol treatment, which exerted a complex anticancer effect in the context of ovarian cancer." (PMID 35379271, 2022). "Our results suggest that the inhibition of TIMP-2 by siRNA and CRISPR/Cas-9 modulate the expression of MMP-2 and MMP-14 and reprogram ovarian cancer cells to facilitate proliferation and invasion." (PMID 36585738, 2022). "The growth and spread of ovarian cancer can be orchestrated by MMP-14 in conjunction with other molecules including MMP-2, TIMP-2 and the integrins." (PMID 34344453, 2021). "Eventually, 59 articles were included in this review on MMP-14 and ovarian cancer: 32 on basic research, 19 on clinicopathological research and 8 in both categories." (PMID 34344453, 2021). "The basic research studies show that MMP-14 plays an important role in ovarian cancer in the processes of proliferation, invasion, angiogenesis and metastasis." (PMID 34344453, 2021). "In a series of 92 serum samples, 26 from patients with ovarian cancer, MMP-14 was found to be significantly increased in the ovarian cancer patients compared to those with benign masses or healthy females." (PMID 34344453, 2021). "The exact translation of these roles in the pathophysiology to the importance of MMP-14 in clinicopathological research in ovarian cancer and possible therapeutic role of anti-MMP-14 agents needs further elucidation." (PMID 34344453, 2021). "With respect to MMP-14, a monoclonal antibody that blocks MMP-14 abrogates invasion, angiogenesis, and tumor growth in ovarian cancer." (PMID 35008569, 2021). "In ovarian cancer, MMP-14 seems to play an important role in invasion and metastasis as well as in proliferation and angiogenesis, though the latter two processes have been less well studied." (PMID 34344453, 2021). "From this systematic review of current knowledge regarding the role of MMP-14 in ovarian cancer, MMP-14 comes to the forefront as an important molecule in the pathophysiology of ovarian cancer." (PMID 34344453, 2021). "From the various models in this limited number of studies, it can be concluded that MMP-14 seems to play a role in an increase in proliferation of ovarian cancer cells." (PMID 34344453, 2021). "Screening the reference lists of the remaining 61 studies yielded two additional articles on ovarian cancer and MMP-14." (PMID 34344453, 2021). "Koshikawa demonstrated that MMP-14 promotes heparin-binding EGF-like growth-factor-induced proliferation of ovarian cancer cells both in suspension and in collagen gel." (PMID 34344453, 2021).